TP53AIP1 (tumor protein p53 regulated apoptosis inducing protein 1)
Synonyms: p53AIP1
Tractability: No criterion of Open Targets' tractability assessment is met for any kind of drug.
Safety:
Unwanted effects reported when the protein is acted on. In parentheses: how it was acted on, where the effect was seen, and who reports it.
neutropenia (source: ClinPGx)
Gene: Protein-coding gene on chromosome 11 (128,934,731 to 128,943,399, reverse strand). Ensembl gene ENSG00000120471.
Subcellular location: Mitochondrion
Gene Ontology:
Biological process: apoptotic process
Cellular component: mitochondrial matrix; mitochondrion
Genetic constraint (gnomAD): Loss-of-function variants: 19 observed, 9.78 expected, observed/expected ratio (o/e) 1.94, 90% interval 1.25 to 1.97. That is too few expected variants to judge how well the gene tolerates losing a copy. Missense variants: 153 observed, 137.66 expected, observed/expected ratio (o/e) 1.11, 90% interval 0.97 to 1.27. Synonymous variants: 73 observed, 55.2 expected, observed/expected ratio (o/e) 1.32, 90% interval 1.09 to 1.61.
Homologues: Orthologues: chimpanzee TP53AIP1 (98% identical).
Diseases named in the same sentence as TP53AIP1 in open-access papers:
TP53AIP1 is named in the same sentence as 20 diseases in open-access papers, as found by Europe PMC text mining. Sharing a sentence is not in itself a finding about the gene and the disease. The quoted sentences say what the papers report.
breast carcinoma (7 papers, 2020 to 2025). "Another study reports TP53AIP1 as an inducer of autophagy through the AKT/mTOR signaling pathway in a breast cancer cell line." (PMID 40860288, 2025). "To further validate the prognostic value of these genes in breast cancer, we conducted COX regression analysis and found that MGAT4EP exhibited predictive performance for breast cancer prognosis with an AUC > 0.6, specifically AUC = 0.673, while TP53AIP1 showed a lower predictive ability." (PMID 40069131, 2025). "This suggests that TP53AIP1 and ME3 may function as tumor suppressors, and MRPL13 might act as an oncogene in breast cancer." (PMID 38310106, 2024).
lung carcinoma (4 papers, 2009 to 2024). "They concluded that miR-505-5p in plasma EVs can be transferred to lung cancer cells, where it inhibits apoptosis and promotes cell proliferation by targeting TP53AIP1." (PMID 39273095, 2024). "Additionally, miR-505-5p, which is an oncogene, can enhance lung cancer cell growth and inhibit their apoptosis by targeting apoptosis inducing TP53AIP1." (PMID 36225178, 2022). "miR-505-5p promoted lung cancer cell growth via TP53AIP1 and plays the role of oncogenes." (PMID 36225178, 2022).
alexithymia (2 papers, 2023 to 2024). An agnosia that is a deficiency in understanding, processing, or describing emotions. "The exome association analysis detected four significant variants (ABCB4 gene: rs45575636, TP53AIP1 gene: rs35942033, ARHGAP32 gene: rs35287114, and TMEM88B gene: rs144957058) associated with alexithymia." (PMID 39202385, 2024). "Furthermore, there are other genes related to alexithymia risk, such as VDBP, TP53AIP1, ARHGAP32, and TMEM88B." (PMID 39202385, 2024). "Little GWAS data are currently available on alexithymia and emotional dysregulation; more research is needed in this area, as the data currently available already yielded some interesting results (TMEM88B, ABCB4 and TP53AIP1 for alexithymia, and ILR2A for emotional dysregulation)." (PMID 36729042, 2023).
prostate carcinoma (2 papers, 2009 to 2012). A carcinoma that arises from epithelial cells of the prostate gland. "We conclude that there is little support at present to regard TP53AIP1 as a prostate cancer susceptibility gene." (PMID 22457820, 2012). "The large sample size of the combined cohort rejects a high-risk effect greater than 2.2 and indicates a limited role of TP53AIP1 in prostate cancer predisposition." (PMID 22457820, 2012).
cervical cancer (1 paper, 2025). A primary or metastatic malignant neoplasm involving the cervix.
cutaneous melanoma (1 paper, 2025). A primary melanoma arising from atypical melanocytes in the skin. "Loss of function variants in TP53AIP1, including c.63dupG; p.(Gln22Alafs∗81), have been reported previously to result in reduced expression of TP53AIP1 and predispose to cutaneous melanoma." (PMID 40860288, 2025).
hereditary cancer (1 paper, 2021). Malignant neoplasms occurring in families at a rate greater than that expected by chance and caused by germline mutations in a specific gene. "In addition, nonsense variants in apoptosis-related genes TP53AIP1, BCLAF1, and PIK3C2G were identified in our cohort; highlighting the potential relevance of genes involved in apoptotic processes to hereditary cancer." (PMID 33782397, 2021).
lung adenocarcinoma (1 paper, 2025). A carcinoma that arises from the lung and is characterized by the presence of malignant glandular epithelial cells. "In lung adenocarcinoma, miR-505-5p acts as an oncogene by targeting TP53AIP1 to inhibit apoptosis." (PMID 40427523, 2025).
tumor (17 papers, 2007 to 2025). "The expressions of SHISA5, SERPINE1, and IL1A were markedly high in tumor tissues, whereas those of TP53AIP1, ETS2, and FOS were high in the normal tissues." (PMID 38435998, 2024). "The father, who carries this heterozygous variant, does not have skin hyperpigmentation, indicating that haploinsufficiency of TP53AIP1 alone may not cause this phenotype but might increase the likelihood of skin hyperpigmentation." (PMID 40860288, 2025). "Concerning the 8 MRGs expression pattern, 4 genes, namely ACSL1, ALDH2, TP53AIP1, and ME3, were observed to be downregulated in tumor tissues while being upregulated in adjacent-normal tissues." (PMID 38310106, 2024). "The mRNA level of TP53AIP1 increased methylation of promoter regions in PTPRD gene, which in turn possibly diminished the protein level PTPRD, thereby sensitizing tumor cells to oxaliplatin." (PMID 35853873, 2022). "CX3CL1 is TP53AIP1, and Fas and DR5 act as tumor suppressors by promoting cell apoptosis or inhibiting cell migration 31-34." (PMID 34131400, 2021). "Some upregulated genes, such as CX3CL1 31, TP53AIP1 32, Fas 33, and DR5 34, were reported as tumor suppressors." (PMID 34131400, 2021).
cancer (13 papers, 2008 to 2025). A tumor composed of atypical neoplastic, often pleomorphic cells that invade other tissues. "Recent studies have reported that reduced expression of TP53AIP1 is associated with an increased risk of cancer." (PMID 40860288, 2025). "Although there is growing evidence for the role of TP53AIP1 in various cancers, further functional investigation is required to examine the direct interaction of well-established cancer risk genes in conjunction with pathogenic TP53AIP1 variants in increasing cancer severity." (PMID 40860288, 2025). "Inhibited TP53AIP1 expression impairs the ability to induce apoptosis in cancer cells." (PMID 37256211, 2023). "Low TP53AIP1 expression in various cancers promotes cancer progression." (PMID 37256211, 2023). "Genes whose median expression was below the threshold in more than half of the cancer types were common in cohorts A and B (ADGRB1, IGF1, RPRM, TP53AIP1)." (PMID 36964217, 2023). "The expression level of GSTP1, FAM83H, TP53AIP1, and PKP3 were all reported to be involved in the development of cancer or affecting patients’ survival rate." (PMID 35776767, 2022). "In unstressed cancer cells TRIM28 represses the expression of pro-apoptotic genes: TP53AIP1, BAX, BBC3 (PUMA) and PMAIP1 (NOXA), further suggesting that TRIM28 provides survival advantage to cancer cells." (PMID 28851455, 2017).
TP53AIP1 also shares sentences with these, for which no sentence is quoted: melanoma (2 papers); autism (1); bladder tumors (1); colon cancer (1); emotional dysregulation (1); heart defects (1); non-small cell lung carcinoma (1); preeclampsia (1); schizophrenia (1); triple-negative breast carcinoma (1).